INS (insulin)
Diseases named in the same sentence as INS in open-access papers (continued):
Sharing a sentence is not in itself a finding about the gene and the disease.
Obesity (continued). "However, control of obesity-related parameters such as HOMA-IR and insulin, equivalent gender and age matching within groups, and long-term follow-up are its advantages." (PMID 37112628, 2023). "Moreover, treating the ob/ob mouse model of obesity with BRL 37,344 seemed to rescue from metabolic dysfunction, by improving systemic levels of glucose, FFA and insulin." (PMID 38136585, 2023). "As expected, lean wild-type animals did not present phosphorylation at PPARγ S273, which is induced by obesity, and no alterations in intraperitoneal insulin (ipITT) and glucose (ipGTT) tolerance tests were detected." (PMID 37189379, 2023). "Exercise training is effective for lowering fasting glucose, fasting insulin, HOMA-IR, and BW in children and adolescents with overweight or obesity and could provide an important strategy for controlling IR and related factors." (PMID 37635963, 2023). "Thus, at prepubertal ages there is an association between liver enzyme levels, anthropometric measurements, insulin, and HOMA-IR in children with obesity." (PMID 36894963, 2023). "In clinical practice, insulin levels and insulin resistance are seldom measured, and do not add value in severe obesity." (PMID 37313244, 2023). "OxLDL/HDL correlated with insulin and HOMA-IR in 214 men with obesity with the authors suggesting that these findings confirm the active role of HDL in the reverse transport of lipid peroxidation products away from peripheral tissues which is the opposite to the role of LDL." (PMID 37529617, 2023). "For instance, 12 weeks of high-intensity interval cycling (70%–100% HRmax, 3 sessions/week) exerted a reduced in fasting plasma glucose (−6.6%), fasting insulin (−47.2%), HOMA-IR (−50%), and systolic blood pressure (−6 mmHg) in women (mean age 33.5 years) affected by obesity with IR." (PMID 37608837, 2023). "In adults with T2D, obesity, and HbA1c > 9%, without severe signs or symptoms of hyperglycemia, a combination of basal insulin and GLP-1 RA therapy SHOULD BE CONSIDERED to improve glycemic control." (PMID 37468901, 2023). "Furthermore, the administration of synthetic adropin promotes glycogen synthesis, attenuates glucose production, and improves insulin sensitivity by raising IRS1/2-Akt phosphorylation and lowering the FoxO1 transcript in mouse models of diet-induced obesity." (PMID 37079136, 2023). "In contrast to metabolically healthy obesity (MHO), metabolically unhealthy obesity (MUO) has unfavorable metabolic profiles characterized by low insulin sensitivity, abnormal blood pressure, and unfavorable lipid, inflammation, hormone, liver enzyme, and immune profiles." (PMID 37512504, 2023). "During obesity, adipose tissue macrophages (ATM) are polarized into pro-inflammatory M1-like macrophages and secrete many pro-inflammatory cytokines, such as TNF, capable of impairing insulin signalling, therefore, promoting the progression of IR." (PMID 36175539, 2023). "When individuals with obesity were categorized according to the insulin sensitivity status, 10 of the 19 insulin-resistant individuals (52.6%) were seropositive for DENV IgM, while only 5 of the 15 insulin-sensitive individuals (33.3%) presented DENV IgM." (PMID 36680274, 2023). "It is worth noting that associations of single dietary FAs and circulating cytokines were found to be independent of the obesity status, of the amount of weight gain during pregnancy, and of the insulin levels as the mediation analysis demonstrated." (PMID 37299395, 2023). "These associations were mainly observed in women and in subjects without obesity, and were independent of insulin sensitivity." (PMID 36902180, 2023). "The mechanisms of impaired glucose-induced insulin secretion from the pancreatic β-cells in obesity have not yet been completely elucidated." (PMID 37863964, 2023).
Obesity (continued). "The reason why obesity was related to EOCRC may be that obesity is involved in the occurrence and development of CRC by affecting metabolism and inflammatory factors, including insulin and insulin-like growth factors, sex hormones, and adipokines." (PMID 37213277, 2023). "Therefore, obesity or T2DM models, effective inhibition of NLRP3 inflammasome activation reduces the inflammatory response of β cells, thereby improving insulin sensitivity by inhibiting the production of IL-1β." (PMID 36993972, 2023). "Obesity and diabetic conditions bring about mitochondria Ca2+ turbulence and thus resulting in mitochondria dysfunction, which collectively aggravate T2DM progression by abolishing insulin signaling." (PMID 37303813, 2023). "In this randomized, controlled, crossover trial, nine non-diabetic insulin-resistant volunteers with obesity, aged 49 ± 7 years, were subjected to two periods of supplementation (placebo and PPEP) for 3 months." (PMID 37627476, 2023). "In support of this conclusion, in our study of adults without obesity, the postprandial decrease in plasma AG was not correlated with the postprandial increase in insulin." (PMID 37287649, 2023). "This was possible thanks to the study of a well-characterized population comprising children and adolescents with obesity, who underwent an OGTT with the aim of assessing their capacity of properly secreting insulin in response to a glycemic challenge (i.e., early vs. late responders)." (PMID 37242230, 2023). "Recently, it has been shown that deterioration in β-cell insulin secretion capacity, not insulin sensitivity, is a determinant of impaired fasting glucose that ultimately leads to T2D in people with obesity." (PMID 38026205, 2023). "Similarly, vitamin E has been described as potential antioxidant and anti-obesity factor able to reduce collagen deposition in visceral adipose tissue of high fat-diet (HFD) mice, inducing insulin sensitivity improvement." (PMID 38169845, 2023). "Rexinoids also decrease hyperglycemia and hyperinsulinemia by improving skeletal muscle insulin sensitivity in mouse models of obesity and noninsulin–dependent diabetes." (PMID 37714463, 2023). "We also found that obesity, increased HDL levels, and insulin insensitivity in SMS mice could be partially alleviated using a small molecule drug (LM22A-4) that promotes AKT phosphorylation." (PMID 37956053, 2023). "Although not all individuals with obesity are insulin resistant, there is a well-demonstrated connection between these two phenomena, which is largely attributed to adipose and others tissues’ metabolic dysfunctions." (PMID 37513538, 2023). "Supplementation with CTE did not prevent the obesity-induced increase in glycaemia but it significantly reduced the plasma concentrations of leptin (p < 0.01), adiponectin (p < 0.05) and insulin (p < 0.05), as well as the HOMA-IR (p < 0.05)." (PMID 37239868, 2023). "During obesity, VEGF secretion increases in an insulin-dependent manner." (PMID 37014444, 2023). "The LGI diet has been of particular interest to the population with obesity, as it was proven that it can slow down insulin secretion, attenuate the postprandial glucose response, and prolong satiety in non-diabetic subjects with obesity." (PMID 37761441, 2023). "A small clinical trial of participants with obesity (NCT00771901) showed that TUDCA can improve insulin sensitivity in liver but not adipose tissue." (PMID 37296593, 2023). "Pemt–/– mice do not develop obesity with high-fat feeding, retain insulin sensitivity, and have lower leptin concentrations compared with littermate controls." (PMID 36472923, 2023). "In a double-blind, RCT trial during which healthy subjects consumed zero, two and four egg yolks per day for 4 weeks, the LDL-c rise with egg feeding was attenuated in insulin resistant participants, regardless of obesity status." (PMID 37375561, 2023).
Obesity (continued). "In contrast to what we observed in mice with CerS6 deficiency in Nkx2.1-expressing cells, inhibiting CerS1 in neurons of the hypothalamus did not affect HFD-induced obesity, systemic insulin sensitivity, or glucose tolerance." (PMID 38016943, 2023). "The authors determined the level of expression of LEP in PCOS patients with or without obesity and in GCs treated with insulin." (PMID 37562217, 2023). "The biochemistry parameters indicated significant differences in glucose, insulin, HOMA-IR, Homa-beta, and hs-PCR among the participants with obesity class III and class IV compared to those with class I and class II, with the higher BMI classes presenting the less healthy results (p < 0.01)." (PMID 37444110, 2023). "According to this study, supplementation with standardized PPEP for 3 months in non-diabetic insulin-resistant volunteers with obesity led to an improvement in insulin homeostasis by its effect on insulin resistance and secretion." (PMID 37627476, 2023). "Interestingly, L-selenomethionine diet supplementation has been associated with an enhanced adipose tissue beiging process in HFD-induced obesity, while oral glutathione (GSH) supplementation improves insulin sensitivity in obese subjects." (PMID 38169845, 2023). "Obesity exerts a multitude of effects both locally and systematically, through a series of inflammatory mediators (increased leptin, reduced adiponectin, TNF-α, IL-6), growth factors (insulin, IGF-1), and metabolism molecules (visfatin, grehlin, and resistin)." (PMID 37834153, 2023). "Acute cold exposure further augmented ß-adrenergic signaling in Plin5-Tg mice, whereas housing at thermoneutrality did not protect Plin5-Tg mice from HFD-induced obesity albeit blood glucose and insulin levels remained low in transgenic mice." (PMID 37150323, 2023). "In male mice, LR treatment did not affect insulin sensitivity in obesity, but it did ameliorate depressive-like behavior." (PMID 37881580, 2023). "Histone acetylation was positively correlated with obesity indices, TNF-α, insulin, and HOMA-IR." (PMID 37862340, 2023). "In women with overweight or obesity with a family history of breast cancer, but without previous disease, IF reduced percentage body fat, fasting insulin, and HOMA compared to continuous calorie restriction." (PMID 37296485, 2023). "WBISI and oDI are not the gold standard approaches for measuring insulin sensitivity and β-cell function; however, they have been validated or compared against their respective gold standard in youth with obesity." (PMID 37299403, 2023). "Moderate overconditioning, or obesity without insulin dysregulation seem to be tolerable and even favorable to the mare from a fertility point of view." (PMID 37152686, 2023). "Obesity-related inflammation and IR can also promote the conversion of HCC cells to the glycolytic pathway through upregulation of the different growth factors (insulin, IGF1) and ROS." (PMID 37266440, 2023). "Here we hypothesize that we can mimic the rescue mechanism of adipose tissue against obesity by supplementing high dose POA exogenously, which will improve whole-body insulin sensitivity and ameliorate hepatosteatosis." (PMID 38313838, 2023). "Thus, we selected obesity-related in vitro conditions, including glucose, insulin, TNF-α, IL-6, PA, LA, and Chol, to mimic obesity status." (PMID 37047207, 2023). "Our study aimed to investigate the changes in hepatic endoplasmic reticulum (ER) stress, inflammation, insulin signaling, and lipid metabolism during the administration of a high-fat diet (HFD) in mice in order to identify correlations between obesity and metabolic disease development in the liver." (PMID 37229466, 2023). "DGAT1 knockout mice are resistant to obesity and insulin without changes in TAG levels in a high-fat diet-induced murine model." (PMID 37233656, 2023).
Obesity (continued). "Dysregulated insulin secretion and/or clearance resulting in chronically elevated insulin or hyperinsulinemia, without hypoglycemia is common in obesity and metabolic disorders." (PMID 37200851, 2023). "A systematic review of all three randomized placebo-controlled studies to treat obesity published to date found no impact of FMT on obesity, fasting plasma glucose, hepatic insulin sensitivity, or cholesterol markers across all included studies." (PMID 36717893, 2023). "Obesity is also a common finding, with a reported prevalence of 30% to 60%, that affects insulin levels regardless of its effects on insulin sensitivity." (PMID 37796920, 2023). "In summary, supplementing the diet of females with overweight/obesity with an HFC beverage for 4 weeks did not improve HOMA-IR or insulin-stimulated glucose disposal." (PMID 36771271, 2023). "Reduced the levels of obesity-related TNF-α and IL-6, reduced fasting glucose and insulin levels." (PMID 36671814, 2023). "In summary, increased MCP-1 and IL-1ra were predictors of insulin sensitivity, independent of age, sex, and adiposity among Latino youth with obesity and prediabetes." (PMID 37299403, 2023). "Although the assessment of the glucose profile and insulin sensitivity indices is common in studies with patients with obesity, overweight, and/or diabetes, none of the studies found for the administration of S. boulardii evaluated these parameters." (PMID 37569390, 2023). "Additionally, HFD-fed mice presented significantly higher serum FBG, insulin, and HOMA-IR levels than the mice in the control group, and these obesity phenotypes were also significantly attenuated by AE." (PMID 37711889, 2023). "This later point is consistent with our current work showing that higher BAIBA levels correlated with lower circulating glucose and insulin at 180 minutes of the OGTT in adults with obesity, independent of PD status." (PMID 37780967, 2023). "A recent study has suggested that adipose tissues rather than adipocytes in obesity subjects were unable to respond to insulin, which partly explained for differential roles of PID1." (PMID 37117198, 2023). "Conversely, a study performed on a different p66Shc-/- mouse model, named ShcL, demonstrated that reduced p66Shc levels improved insulin sensitivity in adipocytes, muscles, and the liver without preventing diet-induced obesity." (PMID 38203279, 2023). "In humans, euglycemic hyperinsulinemic clamps inhibits secretion of total ghrelin in adults without obesity, whereas over a 24-hour period plasma, total ghrelin changes reciprocally with serum insulin in adults without obesity." (PMID 37287649, 2023). "Diet-induced obesity increases the activation of inflammation in the mediobasal hypothalamus, resulting in the production of proinflammatory cytokines (TNF-α, IL-1β, and IL-6) and impairment in insulin and leptin signaling." (PMID 36677011, 2023). "The objective of this study was to evaluate the effect of supplementation with standardized poplar propolis extract powder (PPEP) on insulin homeostasis in non-diabetic insulin-resistant volunteers with obesity." (PMID 37627476, 2023). "Suppressing insulin significantly reduced vagal-induced bronchoconstriction in rats on HFD, suggesting that hyperinsulinemia, rather than obesity alone, underlie obesity-induced bronchoconstriction via parasympathetic nerves." (PMID 36837831, 2023). "Finally, improving insulin sensitivity and browning the WAT by ginseng chemical constituents can increase the capabilities to reduce weight and prevent obesity." (PMID 37408757, 2023). "However, HFD-fed mice lacking both GPR41 and GPR43 were found to exhibit improved glucose tolerance and insulin sensitivity, showing that the role of GPR41 and GPR43 during obesity still needs to be clarified." (PMID 38136564, 2023).
Obesity (continued). "In PDAC, both insulin and IGF-1 are considered to play a role in cancer development and progression, with the PI3K and MAPK signaling pathways as its central pathways, and these signals are enhanced in obesity." (PMID 36755926, 2023). "Mitogen-activated protein kinase phosphatase-1 (MKP-1), an enzyme expressed in the muscle, is abnormally elevated in the skeletal muscle of patients with obesity, and MKP-1 prevents phosphorylation of Akt Ser473 and signaling of molecules such as p38 AMPK, resulting in insulin resistance." (PMID 36918975, 2023). "According to the findings of our systematic review meta-analysis, apart from lifestyle changes, metformin, a classic insulin sensitizer seems to lead to some benefits in children with NAFLD, especially those with obesity, by improving some metabolic syndrome individual parameters." (PMID 37639015, 2023). "Obesity was also accompanied by hyperinsulinemia of both genotypes at the ages of 6 and 10 months; in addition, 10-month-old APP/PS1 mice on a HFD reached insulin levels that were 38-fold higher than those of their controls on a STD and 3-fold higher than those of age-matched WT controls on a HFD." (PMID 37686722, 2023). "Hepatic ERK1/2 activities have been found to be increased in both genetic and diet‐induced obesity mouse models, triggering overall IR and impaired glucose homeostasis, while obese mice with decreased hepatic ERK1/2 showed better systemic insulin and glucose tolerance." (PMID 37303813, 2023). "Obesity is also correlated with increased GC production, which is suggested to have a negative impact on insulin sensitivity." (PMID 37080971, 2023). "12-month programme of newsletters followed by nutrition and resistance training improved insulin and lipid metabolic profiles, although its effect on overweight/obesity was not assessed." (PMID 37299488, 2023). "A. Muciniphila may stimulate increased levels of glucagon-like peptide-1 (GLP-1) through protein P9 on the outer membrane, thereby promoting insulin secretion from pancreatic β-cells and suppressing appetite, ultimately improving T2DM and obesity." (PMID 38260058, 2023). "Visfatin/NAMPT exists in two forms: intracellular NAMPT (iNAMPT) that catalyzes NAD+ biosynthesis and modulates insulin sensitivity and lipid metabolism and extracellular eNAMPT/visfatin, an inflammatory cytokine that activates TLR4/NF-κB signaling in obesity and NAFLD." (PMID 36834782, 2023). "BAT activity may increase the rate of glucose uptake under insulin stimulation in humans; however, the functions of BAT are limited in the presence of obesity and diabetes, which may worsen the related metabolic abnormalities." (PMID 37378828, 2023). "Fasting plasma insulin levels were measured in children with PWS between the ages of 0–12 years and in age‐matched non‐PWS participants with early‐onset major (clinically severe) obesity (EMO) and in healthy‐weight sibling controls (SC)." (PMID 37546289, 2023). "In addition, insulin signaling and MAPK pathways have been reported to be related to metabolic disorders and obesity‐related cancers, especially EC." (PMID 37387559, 2023). "On the other hand, knockout mice lacking Fetuin-A showed improved insulin signaling and prevented obesity development after being fed a high-fat diet." (PMID 37998747, 2023). "In our study, univariate analysis not only indicated a significant relationship of fasting insulin, VAT, MRI liver fat content with glucagon in our cohort of children and adolescents with overweight and obesity, but also with the liver enzyme alanine transaminase (ALT)." (PMID 36133310, 2022). "A composition of phytonutrients comprising berberine, cinnamaldehyde, and curcumin was effective in improving insulin sensitivity without increasing adiposity in a diet-induced obesity murine model." (PMID 36145160, 2022).